NUDT13 (nudix hydrolase 13)
Description:
NAD(P)H pyrophosphatase that hydrolyzes NADH into NMNH and AMP, and NADPH into NMNH and 2',5'-ADP. Has a marked preference for the reduced pyridine nucleotides. Does not show activity toward NAD-capped RNAs; the NAD-cap is an atypical cap present at the 5'-end of some RNAs.
Synonyms: DKFZp586P2219
Tractability: No criterion of Open Targets' tractability assessment is met for any kind of drug.
Gene: Protein-coding gene on chromosome 10 (73,110,375 to 73,131,828, forward strand). Ensembl gene ENSG00000166321.
Subcellular location: Mitochondrion
Pathways (Reactome):
Metabolism: Interconversion of nucleotide di- and triphosphates
Gene Ontology:
Molecular function: NAD+ diphosphatase activity; NADH pyrophosphatase activity; NADPH pyrophosphatase activity; pyrophosphatase activity; hydrolase activity; metal ion binding
Biological process: nucleobase-containing small molecule interconversion
Cellular component: mitochondrion; mitochondrial matrix
Genetic constraint (gnomAD): Loss-of-function variants: 36 observed, 37.99 expected, observed/expected ratio (o/e) 0.95, 90% interval 0.73 to 1.25. The upper end of that interval is the gene's LOEUF score, 1.25, which puts it in group 5 of 6, group 1 being the genes least tolerant of losing a copy. Missense variants: 315 observed, 358 expected, observed/expected ratio (o/e) 0.88, 90% interval 0.8 to 0.97. Synonymous variants: 120 observed, 135.09 expected, observed/expected ratio (o/e) 0.89, 90% interval 0.76 to 1.03.
Homologues: Orthologues: chimpanzee NUDT13 (99% identical), macaque NUDT13 (98% identical), pig NUDT13 (87% identical), dog NUDT13 (85% identical), guinea pig NUDT13 (84% identical), rabbit NUDT13 (82% identical), mouse Nudt13 (78% identical), rat Nudt13 (78% identical), tropical clawed frog nudt13 (53% identical), zebrafish nudt13 (46% identical).
Diseases named in the same sentence as NUDT13 in open-access papers:
NUDT13 is named in the same sentence as 14 diseases in open-access papers, as found by Europe PMC text mining. Sharing a sentence is not in itself a finding about the gene and the disease. The quoted sentences say what the papers report.
breast carcinoma (2 papers, 2023 to 2024). "Despite the p-values for AUCs of some genes such as AP3B2, BLOC1S1, NUDT13, PTCH1, and ZNF609 being statistically significant in all three breast cancer subtypes, their significance in HER2+ cancers and TNBC were much lower compared to that in ER+/HER2- breast cancer patients." (PMID 37700842, 2023).
gastric cancer (2 papers, 2017 to 2022). A primary or metastatic malignant neoplasm involving the stomach. "Expression of UTP23, NUDT13 and CPNE7 are associated with poor prognosis in tumors including ovarian cancer, gastric cancer, oral squamous cell carcinoma." (PMID 36685828, 2022).
adenoma (1 paper, 2025). A neoplasm arising from the epithelium. "Herein, transcriptome profiling of paired early‐stage CRCs and adenomas identifies Nudix hydrolase 13 (NUDT13) as a critical suppressor." (PMID 39921866, 2025). "Among them, 3 genes (NUDT13, PYROXD2, and YPEL3) were validated through RT‐qPCR using a cohort comprising 36 paired early‐stage CRC samples and 14 paired adenomas, as well as through datasets from UCSC Xena." (PMID 39921866, 2025).
colorectal adenoma (1 paper, 2025). An adenoma that arises from the colon or rectum. "This study identified NUDT13 as a roadblock in the progression from colorectal adenoma to CRC, and revealed that NUDT13 stabilizes PKM1 protein by reducing the PARylation that is catalyzed by PARP1, thereby reprogramming the metabolic propensity of CRC cells." (PMID 39921866, 2025). "In conclusion, we identified NUDT13 as a roadblock in the progression from colorectal adenoma to CRC, and revealed that NUDT13 stabilizes PKM1 protein by reducing the PARylation that is catalyzed by PARP1, thereby reprogramming the metabolic propensity of CRC cells." (PMID 39921866, 2025).
cyst (1 paper, 2025). A sac-like closed membranous structure that may be empty or contain fluid or amorphous material. "To explore potential roles of Subclade II NUDTs in plant‐pathogen interactions, we first examined transcript abundance of NUDT12, NUDT13, and NUDT16 during Arabidopsis infection by cyst nematodes (CN) using previously published transcriptomic data." (PMID 41165244, 2025).
intestinal polyp (1 paper, 2025). Discrete abnormal tissue masses that protrude into the lumen of the intestine. "To investigate the involvement of NUDT13 in the transition from intestinal adenoma to carcinoma, we examined NUDT13 levels in the Apc Min/+‐dextran sodium sulfate (DSS) mouse model, a system in which intestinal polyps progress to CRC upon DSS challenge." (PMID 39921866, 2025).
tumor (3 papers, 2017 to 2025). "As expected, the levels of PKM1 were lower in CRC samples compared to their para‐tumor counterparts and exhibited a positive correlation with that of NUDT13." (PMID 39921866, 2025). "Through analysis of the transcriptome profiles extracted from CRC tissues, adenomatous polyps, and para‐tumor tissues, we identified NUDT13 as a hitherto underestimated regulator that can impede malignant colorectal transformation." (PMID 39921866, 2025). "Moreover, subcutaneous tumors in nude mice revealed that PKM1 knockdown restored the tumor growth and tumorigenic potential that had been suppressed by NUDT13." (PMID 39921866, 2025). "However, in subcutaneous xenograft models, NUDT13 overexpression sharply suppressed the tumor growth and tumorigenic potential of CRC cells, and the knockout of NUDT13 accelerated xenograft tumor growth." (PMID 39921866, 2025). "According to the expression levels and regression coefficients, the downregulated BAX, PWP2, SERTAD1, S1PR4, ZFAND1, NUDT13 and ZNF107 with HR < 1 were considered as tumor suppressors, whereas the MVD, BAD, CPNE7, CPNE7, UTP23 and ZNF124 upregulated with HR > 1 were regarded as oncogenes." (PMID 36685828, 2022). "Notably, the PARP1 inhibitor Olaparib significantly reduces tumor burden in Nudt13VillKO mice, implying that CRC patients with low NUDT13 protein levels may benefit from Olaparib treatment." (PMID 39921866, 2025).
cancer (2 papers, 2023 to 2025). A tumor composed of atypical neoplastic, often pleomorphic cells that invade other tissues. "More interestingly, we found that a conserved stretch of NUDT13 (residues 230–252) is necessary and sufficient for mitigating PKM1 PARylation, offering potential for the development of cancer therapeutic strategies." (PMID 39921866, 2025).
infection (1 paper, 2017). The state of being infected such as from the introduction of a foreign agent such as serum, vaccine, antigenic substance or organism. "SDS-PAGE analysis of a cell lysate 48 h after infection showed the presence of a major band corresponding to a 42 kDa protein in cells infected with Nudt13 virus which represented more than 50% of the total cell extract and which was not present in uninfected cells." (PMID 28755312, 2017).
NUDT13 also shares sentences with these, for which no sentence is quoted: colorectal cancer (1 paper); fibroids (1); nematode infection (1); oral squamous cell carcinoma (1); ovarian carcinoma (1).